CDCP2 (CUB domain containing protein 2)
Tractability: Antibody: UniProt predicts a signal peptide or a membrane-spanning region.
Gene: Protein-coding gene on chromosome 1 (54,132,687 to 54,153,770, reverse strand). Ensembl gene ENSG00000157211.
Subcellular location: Membrane
Gene Ontology:
Cellular component: non-collagenous component of interstitial matrix; membrane
Genetic constraint (gnomAD): Loss-of-function variants: 29 observed, 28.88 expected, observed/expected ratio (o/e) 1, 90% interval 0.75 to 1.37. The upper end of that interval is the gene's LOEUF score, 1.37, which puts it in group 5 of 6, group 1 being the genes least tolerant of losing a copy. Missense variants: 432 observed, 490.67 expected, observed/expected ratio (o/e) 0.88, 90% interval 0.81 to 0.95. Synonymous variants: 202 observed, 213.51 expected, observed/expected ratio (o/e) 0.95, 90% interval 0.84 to 1.06.
Homologues: Orthologues: chimpanzee CDCP2 (99% identical), macaque CDCP2 (97% identical), pig CDCP2 (92% identical), rabbit CDCP2 (91% identical), dog CDCP2 (89% identical), mouse Cdcp2 (89% identical), rat Cdcp2 (88% identical), guinea pig CDCP2 (61% identical), tropical clawed frog cdcp2 (58% identical), zebrafish cdcp2 (53% identical). Paralogues in human: CUBN (28% identical), PCOLCE2 (23% identical), PCOLCE (22% identical), CNTNAP2 (13% identical), CNTNAP1 (12% identical), F5 (12% identical), CNTNAP5 (12% identical), CNTNAP4 (12% identical), CNTNAP3 (11% identical), CNTNAP3B (11% identical), NRP1 (11% identical), NRP2 (11% identical), and 23 more.
Diseases named in the same sentence as CDCP2 in open-access papers:
CDCP2 is named in the same sentence as 2 diseases in open-access papers, as found by Europe PMC text mining. Sharing a sentence is not in itself a finding about the gene and the disease. The quoted sentences say what the papers report.
dystocia (1 paper, 2020). Slow or difficult obstetric labor or childbirth. "Previous studies reported that CDCP2, ENSBTAG00000030623 and MROH7 were located within two QTL for body weight and dystocia in Holstein cattle and PCDH8 in a QTL for marbling score in Angus cattle." (PMID 33167870, 2020).
myeloma (1 paper, 2025). "CDCP2 is a protein-coding gene and is associated with osteosclerotic myeloma in humans." (PMID 39943146, 2025).